INS (insulin)
Diseases named in the same sentence as INS in open-access papers (continued):
Sharing a sentence is not in itself a finding about the gene and the disease.
Insulin resistance (continued). "Although fasting blood glucose levels were similar in the studied groups of subjects, serum concentration of fasting insulin and insulin resistance index, HOMA-IR, were significantly higher (p < 0.001, p < 0.001, respectively) in obese participants compared with non-obese controls." (PMID 30388806, 2018). "These low responses to insulin in peripheral tissues, also termed as peripheral insulin resistance, may be related to increased plasma lipid abundance, which ultimately can be accumulated ectopically in nonadipose tissues." (PMID 30532777, 2018). "But in the NGT group, the glucose metabolic status might even deteriorate if the reduction of insulin secretion overcomes the improvement of insulin resistance." (PMID 29853879, 2018). "That study suggested that the systemic pathological conditions occurring in the obese-insulin resistant condition, could induce brain pathological conditions, such as the induction of brain insulin resistance." (PMID 30233495, 2018). "From these speculations, the higher ratio of LMW adiponectin-induced insulin resistance might be secondary to its inhibitory effect on the amelioration of insulin sensitivity induced by HMW adiponectin." (PMID 29494595, 2018). "Serotonin system may play a role in glucose-stimulated insulin secretion in patients with insulin resistance (IR) and decreased insulin sensitivity." (PMID 30123264, 2018). "Insulin resistance and a decrease in insulin production are the characteristics of T2DM." (PMID 30046616, 2018). "Similarly, CoQ provision did not alter signalling responses or GLUT4 expression in any in vitro models of insulin resistance despite improved insulin-stimulated HA-GLUT4 translocation, 2DOG uptake and suppression of lipolysis under these conditions." (PMID 29402381, 2018). "Thus, in addition to providing an epigenetic basis for insulin resistance, these studies also provided several therapeutic research paths, such as the use of anti-inflammatory agents, insulin-sensitizing agents, GR inhibitors, alone or in combination." (PMID 30205460, 2018). "Furthermore, Adipose tissue dysfunction caused by chronic inflammation leads to improper release and increase serum levels of free fatty acids (FFAs), which are known to contribute to insulin resistance through interfering insulin signaling." (PMID 29592806, 2018). "Additionally, GTT and ITT showed that HFD induced insulin resistance while HCD-fed fish had normal insulin sensitivity." (PMID 30405527, 2018). "Conversely, resistin inhibits insulin signals, inducing insulin resistance." (PMID 30294680, 2018). "Increased fasted plasma glucose and insulin levels as well as insulin resistance were observed." (PMID 29673211, 2018). "Moreover, GRK2 KO mice displayed protection and enhanced insulin sensitivity in animal models of obesity and TNFα-induced insulin resistance." (PMID 30147654, 2018). "The intake of HEW1 significantly lowered plasma insulin levels and improved the quantitative indexes of insulin resistance, insulin sensitivity, and pancreatic β-cell functionality (HOMA-IR, HOMA-β, and QUICKI, respectively), but non-significant changes were observed in group treated with HEW2." (PMID 29614007, 2018). "For these reasons, the higher insulin sensitivity observed in young untreated GHD children is widely different from the different degree of insulin resistance shown by adolescents or adults with GHD, in which the change of body composition plays an additional fundamental role." (PMID 29942285, 2018). "Farris and colleagues have suggested that excessive insulin circulation during insulin resistance may lead to reduced degradation of Aβ." (PMID 30249283, 2018). "The metabolic role of IL-6 is extensively studied and there is no consensus if IL-6 is a pro-inflammatory marker directly involved in insulin resistance or an anti-inflammatory marker that increases insulin secretion and beta-oxidation, and improves beta cell function." (PMID 29382850, 2018).
Insulin resistance (continued). "The placenta, which produces several hormones e.g., human placental lactogen, estrogen and progesterone, can cause insulin resistance by reducing the expression of glucose transporter-4 (GLUT4) and causing the dysfunction of β-cell adaptive response for enhancing insulin production." (PMID 30563117, 2018). "Therefore, the STZ/HFD-induced disorders of blood glucose, insulin, and insulin resistance were modulated in the TGPE-treated groups, especially the 5X group." (PMID 29670038, 2018). "The increased INHBE gene expression by insulin despite insulin resistance could be explained by selective insulin resistance." (PMID 29596463, 2018). "The results showed that 50% fraction could increase insulin sensitivity and reduce insulin resistance, as well as decrease the levels of fasting blood glucose, glycated hemoglobin, and glycosylated serum proteins in diabetic mice." (PMID 30320140, 2018). "Obesity-related insulin resistance and chronically elevated insulin concentrations that begin in childhood can induce atherothrombotic mechanisms, reduce fibrinolytic balance, and impair endothelial function, which independently contributes to future cardiovascular events in adulthood." (PMID 30470212, 2018). "The study setting (here, children recruited in schools vs. hospitals in most other studies) and markers used to assess insulin resistance (in the present study, fasting glucose and insulin vs. oral glucose tolerance tests) were also markedly different between these studies and the present study." (PMID 30235828, 2018). "Our data suggest that atorvastatin and diacerein, by attenuating inflammation and sepsis-induced insulin resistance, may be a potential therapy for sepsis through the improvement in insulin sensitivity and signaling in peripheral tissues." (PMID 29760586, 2018). "These lead to insulin resistance and defective secretion of insulin by pancreatic beta-cell." (PMID 30126383, 2018). "Dietary proteins which may modulate insulin sensitivity are thus of specific relevance on the glucose homeostasis for the pregnant women, with respect to the physiological insulin resistance." (PMID 30364240, 2018). "A potentially greater insulin requirement has been reported due to insulin resistance in puberty." (PMID 29537377, 2018). "Carriers of loss-of-function mutations in ABCA1 exhibit impaired insulin secretion without insulin resistance." (PMID 29439145, 2018). "Altogether, these data provide evidences that insulin signaling and/or IGF-1 signaling disruption at multiple levels may result into the alteration of insulin metabolic effects, thus contributing to insulin resistance and T2D." (PMID 30469501, 2018). "The same trend was found in total cholesterol (TC), triglycerides (TG), fasting blood glucose (FBG), insulin, C-peptide, and homeostasis model assessment-insulin resistance (HOMA-IR) levels, resulting in similar or even lower values in high-dose group than those in sham group." (PMID 29772836, 2018). "Indeed, this is the case of insulin signaling components, which are regulated by several miRNAs whose altered expression has been detected in insulin resistance and in T2D." (PMID 30469501, 2018). "Therefore, our results showed that there had been a substantial improvement in insulin sensitivity and insulin resistance, resulting from foxtail millet intervention." (PMID 30326632, 2018). "DM results in hyperglycemia due to defect in insulin secretion and/or insulin resistance." (PMID 31565649, 2018). "The main lifestyle RCT (the DALI Lifestyle Study) found the HE and PA intervention was associated with the least GWG, but there was no significant reduction in the fasting glucose, GDM incidence, or insulin sensitivity (as measured with the homeostasis model assessment insulin resistance (HOMA-IR)." (PMID 30360536, 2018).
Insulin resistance (continued). "Module 5 was mainly involved in regulating insulin-stimulated cellular responses, negative regulation of the glucocorticoid receptor signaling pathway and insulin resistance-related functions and pathways, which was identified as a potential type 2 diabetes-causing module." (PMID 30521536, 2018). "However, hyperinsulinemia and insulin resistance favor the insulin-dependent activation of MAP-kinases (MAPK), which is associated with the elevated expression of proinflammatory and atherogenic factors." (PMID 29615924, 2018). "However, data on metabolic profiles have been conflicting, with studies showing elevated plasma insulin levels indicating insulin resistance, but also normal or even increased insulin sensitivity in comparison to subjects with simple obesity has been reported." (PMID 29371863, 2018). "In mice, the subcutaneous infusion of LPS, to reach levels that simulate the translocation of gut bacterial products, has been shown to induce glucose intolerance, higher insulin levels, insulin resistance, and very interesting increase in body weight accompanied by increases in adipose tissue." (PMID 29434676, 2018). "In the present study we hypothesised that circulating levels of 4-HHE are elevated in diabetic individuals and that 4-HHE can impair insulin responses in skeletal muscle cells and contribute to insulin resistance in vivo." (PMID 29299636, 2018). "Higher levels of insulin andHOMA-IR were found in diabetic group after diabetesinduction as compared to control group (P<0.05).These results showed that HF/HC diet and STZ treatment ledto obvious insulin resistance with higher insulin, glucose andHOMA-IR levels compared to control animals." (PMID 29845798, 2018). "To confirm insulin resistance, we performed insulin (ITT) and glucose (GTT) tolerance tests." (PMID 30013137, 2018). "The associated decrease in plasma TG may also be involved in the decrease in insulin resistance, as it can impair insulin action through over-activity of the glucose-fatty acid cycle." (PMID 30131705, 2018). "Since DAG (FA18:1) has been implicated in hepatic insulin resistance, the unaltered proportion of DAG (FA18:1) in I148M PNPLA3 carriers with fatty liver may explain the normal insulin sensitivity in these subjects." (PMID 30227635, 2018). "Han men had the highest insulin resistance while Kazak men had the highest insulin sensitivity." (PMID 30193578, 2018). "The increased amount of Akkermansia may be related to elevated GLP-1 secretion, elevated serum insulin, and improved insulin resistance." (PMID 29967794, 2018). "Leucine has been identified as a potent insulin secretagogue in pancreatic islets, and studies have shown that dysregulated leucine metabolism in SIRT4 KO mice leads to elevated basal and stimulated insulin secretion, which progressively develops into glucose intolerance and insulin resistance." (PMID 30442871, 2018). "This relationship could be explained by increased insulin sensitivity, lower fasting insulin resistance and lower glycated hemoglobin concentrations, which are induced by moderate amounts of alcohol." (PMID 29558518, 2018). "In the population of all women and men with DM2 in ANCHOR, there were no significant increases in fasting plasma glucose, hemoglobin A1C, insulin, or homeostasis model assessment–estimated insulin resistance (HOMA-IR) following treatment with icosapent ethyl 4 g/day." (PMID 29583081, 2018). "si:ch211-167b20.8 may encode protein phosphatase 1 (PP1) regulatory subunit 3A-like in the insulin resistance and insulin signaling pathways." (PMID 29642853, 2018). "Defective insulin signaling and development of insulin resistance in the liver may affect energy balance and metabolism." (PMID 30024975, 2018). "Therefore, AMPK pathway is attracting attention in the context of enhancement of insulin sensitivity and alleviation of insulin resistance and it is reasonable to evaluate the effect of BLEx on the AMPK pathway." (PMID 29872751, 2018).
Insulin resistance (continued). "At the molecular level, insulin resistance is usually a failure of insulin signaling, resulting in inadequate plasma membrane translocation of glucose transporter 4 (GLUT4)—the primary transporter that is responsible for bringing glucose into the cell to use as energy." (PMID 30373146, 2018). "In our correlation model, leptin demonstrated a negative correlation with insulin, which has been shown to play a role in the modulation of insulin resistance in subjects undergoing a weight loss program." (PMID 30405010, 2018). "Moreover, liver specific silencing of DPP4 lowered plasma insulin, improved glucose uptake, and suppressed insulin resistance in DIO mice." (PMID 30360455, 2018). "RBP4 has also been found to affect the insulin signaling cascade, leading to insulin resistance." (PMID 29747616, 2018). "CoQ supplementation improves insulin sensitivity in vitro and in vivo models of insulin resistance." (PMID 29402381, 2018). "In addition, we utilized IVGTT to measure insulin sensitivity, which is an improvement over previous studies which have used less sophisticated measures to assess insulin resistance." (PMID 29775461, 2018). "Indeed, the results indicated a common insulin resistance induced by Dex in peripheral tissues, which was consistent with the significantly higher level of blood glucose and insulin in Dex-treated goats." (PMID 29568520, 2018). "Pancreatic islet cells respond to insulin resistance by enhancing insulin secretion and cell mass." (PMID 29467962, 2018). "In addition, the potential therapies for obese-insulin resistance are reported as the therapeutic strategies which exert the neuroprotective effects in the obese-insulin resistant condition." (PMID 30233495, 2018). "Insulin resistance is not a simple matter of deficient glucose uptake in response to insulin, but a multifaceted syndrome that significantly increases risk for CV disease." (PMID 30574207, 2018). "Fasting plasma glucose and insulin levels were also markedly lower in the HL group compared with the HU group, resulting in an improved homeostasis model assessment of insulin resistance (HOMA-IR) index in the HL group." (PMID 30008738, 2018). "We further hypothesized that with insulin resistance, mTORC1 activation contributes to the suppression of autophagy in response to high concentrations of insulin, as measured in mice and L6 myotubes." (PMID 30047243, 2018). "Additionally, extra-hepatic driver mechanisms of insulin resistance-mediated steatosis have been suggested, such as impairment of insulin-mediated suppression of lipolysis in white adipose tissue or insulin resistance in skeletal muscle." (PMID 29558460, 2018). "The phenotypes in DKO mice are highly consistent across individuals and include higher body weight, glucose, insulin, total cholesterol levels, plasma triglycerides, pulse pressure, and mean arterial blood pressure, elevated insulin resistance and impaired glucose tolerance." (PMID 30385846, 2018). "Peripheral insulin resistance could promote AD onset by reducing brain insulin uptake and by raising brain levels of Aβ, tau phosphorylation, oxidative stress, proinflammatory cytokines, advanced glycation end products, dyslipidemia, and apoptosis." (PMID 30079520, 2018). "Long term randomized control trials (3 months-7 years) have studied whether giving vitamin D prevents the progression of insulin resistance to prediabetes to Type 2 diabetes due to its effects on augmenting insulin action and secretion." (PMID 29641737, 2018). "Consequently, insulin resistance occurs primarily in the most insulin sensitive tissues such as liver, muscle and adipose tissue, but also in gastrointestinal tract, central nervous system, and in pancreatic β-cells." (PMID 30469501, 2018). "Because hepatic insulin resistance is closely related to fatty liver, we tested the hypothesis that miR199a-5p regulates hepatic insulin sensitivity." (PMID 29540751, 2018).
Insulin resistance (continued). "In obesity-associated insulin resistance, however, the absence of adequate insulin signaling permits unregulated adipose tissue lipolysis due to lipid overload." (PMID 29847581, 2018). "In addition, they induce insulin resistance by inhibiting the insulin receptor tyrosine kinase and other signaling proteins, further increasing the physiological demand for insulin secretion." (PMID 29621153, 2018). "Insulin resistance is mediated by high circulating levels of free fatty acids and by the release of certain hormones and inflammatory cytokines from adipose tissue, which impair insulin signaling in insulin sensitive tissues." (PMID 30248999, 2018). "For instance, while insulin resistance may account for the higher insulin levels, and the higher insulin and glucose levels may account for liver fat accumulation, the reasons for insulin resistance and higher glucose levels in these animals are unknown." (PMID 29773828, 2018). "The importance of regulating factors of eNOS expression, such as elevated levels of circulating insulin and insulin resistance (HOMA-IR index) is possibly different in both conditions, since insulin levels and HOMA-IR were increased in LTS rats but not in STS rats." (PMID 29882756, 2018). "Insulin resistance measured using HOMA-IR has been shown to be inversely associated with bone size, potentially explained by high levels of insulin being inversely associated with sex hormone-binding globulin (SHBG), thus increasing the free concentrations of androgens and estrogens." (PMID 29946974, 2018). "Insulin resistance leads to inefficient use, and thus elevated circulating levels, of insulin." (PMID 29710852, 2018). "The models studied included adipose tissue from mice fed a high fat high sucrose diet (HFHSD) for different periods of time and three in vitro models of insulin resistance (3T3-L1 adipocytes treated with chronic insulin, dexamethasone or tumour necrosis factor-α)." (PMID 29402381, 2018). "In order to investigate whether four flavonoids have a positive influence on insulin resistance, we analyzed their effects on glucose uptake in insulin-resistant HepG2 cells." (PMID 30420897, 2018). "Additionally, our data indicated that RSV increased serum SOD activity, ameliorated oxidative stress, increased insulin concentration, and decreased insulin resistance." (PMID 31565649, 2018). "An additional contributing factor, suggested by Dunaif, is the possibility of a defect in the primary steps of insulin signaling, which could result in insulin resistance in women with PCOS." (PMID 29462993, 2018). "Our findings suggest that increased adiponectin secretion from adipose tissue mediated by IRAK inhibitor may increase the insulin sensitivity in an animal model of insulin resistance." (PMID 31565650, 2018). "In type 1 diabetes this is exclusively achieved by exogenous insulin injection; in type 2 diabetes, a variety of medications are available to lower insulin resistance or amplify any residual insulin secretion; basal and prandial insulin injections are increasingly used as well." (PMID 32232090, 2018). "Thus, women with high free T have numerous characteristics of PCOS: ovarian aspects (an increase in AMH as well as ultrasound features), hormonal aspects (a higher LH/FSH ratio), and also metabolic aspects (BMI, insulin levels, and insulin resistance)." (PMID 30275830, 2018). "Furthermore, it has been shown that the presence of excessive lipids within the liver is able to decrease the efficiency of insulin signalling resulting in insulin resistance." (PMID 29351564, 2018). "Furthermore, it has been established that inflammatory cytokines TNF-α and IL-6 inhibit the expression of insulin signaling mediators in adipose tissue leading to a worsening of whole-body insulin resistance and glucose intolerance." (PMID 30510798, 2018).